EGFR (epidermal growth factor receptor)
Diseases named in the same sentence as EGFR in open-access papers (continued):
Sharing a sentence is not in itself a finding about the gene and the disease.
lung adenocarcinoma (continued). "Importantly, this hypothesis is consistent with findings in gene expression studies performed on specific clinicopathological (smoking) or mutation subgroups (EGFR/KRAS) in lung adenocarcinoma." (PMID 27437773, 2016). "In the era of molecular and personalized therapeutics, the discovery of mutations in EGFR in 15-20% of lung adenocarcinomas and the associated response to EGFR-targeting tyrosine kinase inhibitors have provided a successful avenue of treatment in high-stage lung adenocarcinomas." (PMID 26646588, 2016). "Advances in the treatment of patients with lung adenocarcinoma were made with the introduction of molecularly targeted approaches, such as the use of tyrosine-kinase inhibitors for patients with tumors containing activating, sensitizing EGFR mutations and Crizotinib for ALK rearrangements." (PMID 27081085, 2016). "TLGWBR provides a strong prognostic indicator and could be an important guide for making treatment decisions in advanced lung adenocarcinoma patients with EGFR mutation status; however, it cannot be used to further stratify the risk of worse OS for patients with the EGFR mutation." (PMID 27336755, 2016). "However, the EGFR-TKIs sensitive mutation rate of 41.8% in lung adenocarcinoma is lower than the rate of 66.3% in a study with a cohort in Southern China, but much higher than the mutation rate of 7.5% in the study with a cohort of Northern European populations." (PMID 27992557, 2016). "Secondly, our findings suggest that the combination of EGFR-TKIs with other anti-cancer therapeutics may be a rational treatment strategy for patients with lung adenocarcinomas concurrently harboring a somatic EGFR L858R mutation in the tumor and a germline MLH1 V384D polymorphism." (PMID 25823662, 2015). "Although the co-occurrence of EGFR mutations and amplifications has been observed before, it is typically much less pronounced than was observed in our study (e.g., the recent whole-genome analysis of 183 lung adenocarcinomas with the use of massively parallel sequencing)." (PMID 25719557, 2015). "The correlation between EGFR mutation status and clinicopathological features identified in this study suggest that the prognosis may differ according to the EGFR status among clinical stage I lung adenocarcinomas, and that further study is necessary." (PMID 26496308, 2015). "Since the cellular localization of β-catenin should at least in part reflect the activity of the β-catenin pathway, we examined whether β-catenin localization in lung adenocarcinoma tissues with an EGFR mutation is associated with primary resistance to gefitinib." (PMID 26268703, 2015). "Furthermore, since the status of EGFR mutation in patients with advanced lung adenocarcinoma may change during the process of therapy, multiple biopsies may be required and this presents a challenge to both the patients and physicians." (PMID 24587142, 2014). "Therefore, Nrf2 may be a useful biomarker in predicting response of EGFR-TKIs in patients with advanced-stage lung adenocarcinoma harboring EGFR gene mutations." (PMID 24581168, 2014). "We selected formalin-fixed paraffin embedded lung adenocarcinoma specimens that showed discrete areas of different subtypes, extracted subtype DNA samples from those areas and screened for mutations in hotspot regions of the EGFR, KRAS and BRAF genes using high resolution melting." (PMID 24742923, 2014). "To elucidate whether DDX3X expression was correlated with CSC-like properties, we transfected PC9 cells, lung adenocarcinoma cells harboring an EGFR exon 19 deletion mutation, with cDNA encoding DDX3X and established a novel cell line, termed A-1 cells, which overexpressed DDX3X." (PMID 25343452, 2014). "These efforts become evident by comparing the median overall survival of lung adenocarcinoma patients under standard therapeutic regimes of approximately 12 months with approximately 2 years under EGFR-targeted therapy with Erlotinib or Gefitinib in EGFR-mutated cancers." (PMID 24879454, 2014).
lung adenocarcinoma (continued). "Although the underlying mechanism of lung adenocarcinoma is still under investigation, studies showed that recurrent mutations in the epidermal growth factor receptor (EGFR) and the anaplastic lymphoma kinase (ALK) fusions could change the efficacy of treatment for patients with lung adenocarcinoma." (PMID 24646369, 2014). "To identify copy number alterations (CNAs) of general importance in lung adenocarcinoma, which may serve as basis for supervised comparisons between EGFR-mutated, KRAS-mutated and EGFRwt/KRASwt tumors, we analyzed 1272 tumors and cell lines profiled by SNP or aCGH microarrays." (PMID 24205279, 2013). "Thus, the present study aimed to investigate whether -216G/T (rs712829), a functional polymorphism of the EGFR promoter that is able to induce EGFR activation and overexpression, is associated with the pleural metastasis of lung adenocarcinoma." (PMID 24137392, 2013). "Furthermore, these results provide new evidence that EGFR mutant lung adenocarcinoma may have distinct miRNAs associated with overall survival." (PMID 24282590, 2013). "Furthermore, the association between plasma miRNAs and overall survival of lung adenocarcinoma may differ by the status of EGFR mutation." (PMID 24282590, 2013). "Given that we tested a single cell line it remains unclear whether autophagy is common to many cell lines or strictly a mechanism of resistance seen in EGFR mutated lung adenocarcinoma and it is unlikely that all cancer cell lines harbor autophagy as a sole mechanism of resistance." (PMID 23119048, 2012). "Mutations in the EGFR may be involved in the pathogenesis of lung adenocarcinoma." (PMID 24212826, 2011). "used a genome‐wide CRISPR–Cas9 library screen to identify integrin subunit alpha 8 (ITGA8) as a gene that increases the sensitivity of lung adenocarcinoma cells to EGFR‐TKIs." (PMID 41537447, 2026). "Here, we report the case of a 53-year-old man with EGFR L858R-mutant stage IV lung adenocarcinoma who developed multifocal progression involving the lungs, liver, bones, and brain after multiple prior treatments." (PMID 41836239, 2026). "The final diagnosis was stage IV lung adenocarcinoma with a concurrent EGFR exon 19 deletion and EML4‐ALK fusion." (PMID 41497773, 2026). "We report a 71-year-old woman with resectable EGFR-mutant lung adenocarcinoma and concurrent active COVID-19 pneumonia." (PMID 42131806, 2026). "EGFR and KRAS mutations are common oncogenic drivers in lung adenocarcinoma and serve a crucial role in tumorigenesis." (PMID 41268614, 2026). "Elucidating the mechanistic interplay between SOX9 and the EGFR/KRAS pathways in lung adenocarcinoma holds promise for identifying novel therapeutic targets and developing precision medicine strategies." (PMID 41268614, 2026). "This article reports a case of a patient with EGFR-sensitive mutant lung adenocarcinoma who developed secondary transformation to small cell lung cancer (SCLC) and anaplastic lymphoma kinase (ALK) gene fusion following first-line Osimertinib therapy." (PMID 42290055, 2026). "In vitro, tamoxifen upregulated phosphorylated EGFR (p-EGFR) in EGFR-mutant lung adenocarcinoma cell lines." (PMID 41597172, 2026). "Osimertinib is the standard first-line therapy for EGFR-mutant lung adenocarcinoma; however, the inevitable development of acquired resistance leads to disease progression and treatment failure." (PMID 42026030, 2026). "Third-generation epidermal growth factor receptor tyrosine kinase inhibitors (EGFR-TKIs) represent a significant advancement in the targeted therapy of lung adenocarcinoma (LUAD), markedly prolonging patient overall survival." (PMID 41922310, 2026). "This work provides mechanistic insight into stress-adaptive Osimertinib resistance and identifies potential therapeutic targets for overcoming resistance in EGFR-mutant lung adenocarcinoma." (PMID 42026030, 2026).
lung adenocarcinoma (continued). "This study offers novel insights by jointly evaluating the prognostic value of serum markers in patients with lung adenocarcinoma and bone metastases treated with EGFR-TKI." (PMID 41551443, 2026). "Small-cell transformation is a clinically resistant mechanism against epidermal growth factor receptor tyrosine kinase inhibitors (EGFR-TKIs) in lung adenocarcinoma (LUAD)." (PMID 41971422, 2026). "We report a case of EGFR exon 19-mutant lung adenocarcinoma that developed an acquired CCDC6-RET fusion following treatment with first-line osimertinib, identified through repeat molecular profiling at disease progression." (PMID 41694974, 2026). "This research successfully developed a nomogram based on the Cox regression model to predict prognosis and treatment outcomes in patients with lung adenocarcinoma and bone metastases undergoing EGFR-TKI therapy." (PMID 41551443, 2026). "It increases responsiveness to EGFR‐TKIs by suppressing proliferation, invasion and migration of lung adenocarcinoma cells." (PMID 41537447, 2026). "CT-guided lung biopsy confirmed lung adenocarcinoma, and genetic testing revealed an EGFR exon 19 deletion." (PMID 42206169, 2026). "This case underscores the critical importance of retesting for resistant mechanisms, such as EML4‐ALK fusion, in patients with EGFR‐mutant lung adenocarcinoma who experience rapid progression on EGFR‐tyrosine kinase inhibitor (TKI) therapy." (PMID 41497773, 2026). "We describe two patients with advanced lung adenocarcinoma harboring EGFR Ex19del who received furmonertinib plus pemetrexed." (PMID 41695371, 2026). "This study evaluated the prognostic predictive value of the combined application of serum markers (NLR, CEA, and Cyfra21-1) in patients with lung adenocarcinoma bone metastases receiving EGFR-TKI therapy." (PMID 41551443, 2026). "Mechanistically, the EGFR signaling pathway promoted the expression of miR-651-5p by activating the transcription factor Fos proto-oncogene (FOS) in EGFR-mutant lung adenocarcinoma cell lines." (PMID 40002895, 2025). "The case presents a novel METex14 skipping mutation that emerges subsequent to the progression of advanced lung adenocarcinoma following EGFR-TKI treatment." (PMID 40129940, 2025). "Furmonertinib, an EGFR-targeted drug, and its bioactive metabolite AST5902 were tested on A549 and H1975 cell line-based 3D LC models, as A549 is an EGFR wildtype lung adenocarcinoma cell while H1975 is an EGFR mutant one." (PMID 40416783, 2025). "We report a case of partial transformation to SCLC in EGFR-driven lung adenocarcinoma for the first time." (PMID 40134592, 2025). "EGFR-mutant lung adenocarcinomas (LUADs) that are vulnerable to the EGFR antagonist osimertinib (Osi) eventually relapse, owing in part to the emergence of drug-tolerant persister (DTP) cells that arise through epigenetic mechanisms." (PMID 41364502, 2025). "For EGFR-mutant lung adenocarcinoma patients, OS was shorter than for patients harboring a single EGFR mutation (95% CI: 28.2 to NA months; p = 0.006)." (PMID 40076686, 2025). "In this study, 41.83% of 208 patients with early-stage lung adenocarcinoma had EGFR gene rearrangements and 7.69% had ALK gene rearrangements." (PMID 41020204, 2025). "We report a case of a 61-year-old woman with stage IVB lung adenocarcinoma harboring an ERBB2 exon 20 insertion (p.Y772_A775dup) and a concurrent EGFR mutation, who was treated with first-line pyrotinib monotherapy." (PMID 41426315, 2025). "There is no clinical study on the relationship between three-dimensional CT imaging findings and EGFR and ALK gene rearrangements or prognosis in GGO-associated lung adenocarcinoma." (PMID 41020204, 2025). "We conducted a retrospective study of patients with advanced lung adenocarcinoma harboring ALK, ROS1, and RET fusions, comparing them with cohorts harboring EGFR mutations." (PMID 40751559, 2025).
lung adenocarcinoma (continued). "For the first time, a study evaluated a dual EGFR-TKI approach, combining gefitinib (an EGFR inhibitor) with nilotinib, in patients with EGFR-mutated lung adenocarcinoma and Bcr-Abl1-positive CML." (PMID 41155542, 2025). "We then investigated the correlation between PD-L1 tumor proportion score (TPS), TLS expression, and clinical outcomes in early-stage EGFR-mutant lung adenocarcinoma." (PMID 40723259, 2025). "MCAM can enhance the resistance of EGFR-mutant lung adenocarcinoma cells to EGFR-TKIs, both in vitro and in vivo." (PMID 40713600, 2025). "Epidermal growth factor receptor (EGFR) and anaplastic lymphoma kinase (ALK) gene rearrangements are risk factors for the progression of lung adenocarcinoma." (PMID 41020204, 2025). "Dysregulated MET signaling, such as MET overexpression or MET amplification (METamp), is a important mechanism of resistance to EGFR tyrosine kinase inhibitors (TKIs) in patients with EGFR-mutant lung adenocarcinoma (LUAD)." (PMID 40470164, 2025). "A single-center retrospective cohort analysis included 17 treatment-naïve patients with locally advanced/metastatic EGFR-mutant (ex19del/L858R) lung adenocarcinoma." (PMID 41479790, 2025). "A 69-year-old-female with a long-standing history of a seizure disorder was diagnosed with stage IV EGFR exon 19 deletion positive lung adenocarcinoma." (PMID 40256355, 2025). "A 65-year-old man presented with cough and dyspnea and was diagnosed with stage IV EGFR exon 19 deletion well-differentiated lung adenocarcinoma (TTF-1+/CK7+), with metastases involving the right pleura, bilateral lungs, mediastinal lymph nodes, and bones." (PMID 41256964, 2025). "Here we assembled a large international clinical dataset of digital lung adenocarcinoma slides (N = 8,461) to develop a computational EGFR biomarker." (PMID 40634781, 2025). "EGFR and ALK mutations are recognized as critical drivers in the development of NSCLC, especially lung adenocarcinoma, and serve as important targets for clinical therapy." (PMID 41378298, 2025). "A total of 150 lung adenocarcinoma patients were enrolled based on the inclusion and exclusion criteria, comprising 89 EGFR-mutant cases and 61 wild-type cases, with 72 males and 78 females (mean age 60.02 ± 9.15 years)." (PMID 41244899, 2025). "Our findings are in agreement with another report showing that elevated CD109 levels activate EGFR-AKT-mTOR signaling in lung adenocarcinoma cells." (PMID 40317079, 2025). "Tumor cell EGFR expression in canine lung adenocarcinomas was also positively correlated to intratumoral vessel VEGFR2 expression." (PMID 40969344, 2025). "In molecular biology experiments, we demonstrated that ginsenoside Rg3 down-regulated the copy number of 18, 19, 20, and 21 exons and protein expression of EGFR in lung adenocarcinoma cells." (PMID 40732366, 2025). "This case illustrates a rare instance of prostatic metastasis from EGFR-mutant lung adenocarcinoma and emphasizes the critical role of repeat biopsy, molecular profiling, and multidisciplinary evaluation in atypical metastatic presentations." (PMID 40740944, 2025). "A total of 17 patients with locally advanced or metastatic EGFR-mutant lung adenocarcinoma were retrospectively enrolled." (PMID 41479790, 2025). "Mutations in the KEAP1‐NRF2 pathway are relatively rare, accounting for 7% of patients with EGFR‐mutant lung adenocarcinoma in one study." (PMID 39727229, 2025). "Data in this study mirror this finding, in that 80% of canine lung adenocarcinomas were EGFR-positive by IHC with greater than 20% of neoplastic cells staining positive." (PMID 40969344, 2025). "Univariate analysis of the effects of EGFR gene mutation and ALK gene mutation on pathological features of invasive lung adenocarcinoma." (PMID 41378298, 2025). "Melanoma cell adhesion molecule (MCAM), a highly glycosylated type I transmembrane protein belonging to the immunoglobulin superfamily, is upregulated in EGFR-TKI-resistant EGFR-mutant lung adenocarcinoma." (PMID 40713600, 2025).
lung adenocarcinoma (continued). "In investigations involving other tumor types, it has been observed that transformed neuroendocrine carcinomas often emerge in lung adenocarcinomas treated with anti-EGFR therapy and prostate adenocarcinomas subjected to androgen deprivation therapy." (PMID 40842588, 2025). "Here, RAC1B is found to be significantly upregulated in lung adenocarcinoma (LUAD) patients, particularly in those harboring EGFR mutations." (PMID 40548642, 2025). "Our findings provided compelling evidence that CREPT depletion substantially attenuated proliferation and tumorigenesis in LUAD cells harboring KRAS or EGFR mutations, and impaired KRASG12D-induced lung adenocarcinoma formation in vivo." (PMID 40860160, 2025). "A 65-year-old Caucasian woman with a four-year history of stage IV EGFR-positive lung adenocarcinoma presented with a new firm violaceous nodule with minimal scale on the left lower chest wall beneath the breast." (PMID 41542005, 2025). "To validate the existence of TLSs in early-stage EGFR-mutant lung adenocarcinoma, we performed immunohistochemical (IHC) staining on continuous formalin-fixed and paraffin-embedded (FFPE) tumor surgical sections." (PMID 40723259, 2025). "Research has established that mutations in EGFR and KRAS, as well as EML4-ALK fusions, represent the most common driver alterations in lung adenocarcinoma." (PMID 41153394, 2025). "Epidermal growth factor receptor (EGFR) is the most common genetic alteration in lung adenocarcinoma, accounting for approximately 60% of cases in Asian patients." (PMID 40963567, 2025). "TCGA database analysis showed that miR-651-5p was significantly higher in EGFR-mutant than wild type lung adenocarcinoma tissues." (PMID 40002895, 2025). "Here, we present the first documented case of a patient with EGFR H773_V774delinsLM-mutant lung adenocarcinoma who experienced remarkable tumor regression following treatment with furmonertinib." (PMID 40640099, 2025). "Targeted therapies against the epidermal growth factor receptor (EGFR) have markedly improved treatment outcomes for patients with EGFR‐mutant lung adenocarcinoma." (PMID 41263395, 2025). "Here, we present the first case demonstrating the anti‐tumor efficacy of afatinib in a patient with EGFR L861R‐positive lung adenocarcinoma." (PMID 41350121, 2025). "Proteomic and phosphoproteomic analyses were performed on lung adenocarcinoma (LUAD) tumors with EGFR, KRAS, or EML4–ALK alterations and wild‐type cases." (PMID 40621945, 2025). "For instance, single-cell sequencing has revealed that lung adenocarcinoma can undergo transdifferentiation into squamous cell carcinoma under the selective pressure of EGFR-TKI treatment." (PMID 40003951, 2025). "A previous study showed that a patient with EGFR L861R‐positive lung adenocarcinoma treated with afatinib and bevacizumab as second‐line treatment had a PFS of 2 months." (PMID 41350121, 2025). "Our predictive model integrating spectral CT parameters, AI-quantified imaging biomarkers, and clinical indicators demonstrated discriminative capability for EGFR-mutant versus wild-type lung adenocarcinoma, achieving an AUC of 0.713 (95% CI: 0.628-0.797)." (PMID 41244899, 2025). "Univariate analysis of the effects of EGFR gene mutation and ALK gene mutation on radiological features of invasive lung adenocarcinoma." (PMID 41378298, 2025). "Osimertinib resistance poses a major challenge in treating advanced EGFR-mutant lung adenocarcinoma (LUAD)." (PMID 41145422, 2025). "Resistance to epidermal growth factor receptor (EGFR)-tyrosine kinase inhibitor (TKI) remains a critical clinical challenge in EGFR mutant lung adenocarcinoma (LUAD)." (PMID 40897859, 2025).